MIMS1 (mitochondrial inner membrane scaffold 1)
Description:
Mitochondrial inner membrane protein essential for mitochondrial homeostasis, structural integrity, and cellular metabolism. Regulates mitochondrial translation by modulating protein synthesis of mitochondrial DNA-encoded genes. Plays a critical role in skeletal muscle mass and strength by regulating mitochondrial density, function, and protein synthesis. In brown adipose tissue, regulates mitochondrial cristae remodeling in response to cold stress by interacting with mitochondrial protease YME1L1 and enhancing its proteolytic activity, promoting OMA1 degradation and regulating OPA1 processing. Required for cardiac mitochondrial homeostasis and normal cardiomyocyte contractile function. In skeletal muscle, positively regulates myoblast differentiation by enhancing expression of myogenic factors.
Synonyms: C18orf19; FAM210A; MGC24180; HsT2329
Tractability: Antibody: UniProt predicts a signal peptide or a membrane-spanning region. PROTAC: ubiquitination databases record sites on it; its protein half-life has been measured.
Gene: Protein-coding gene on chromosome 18 (13,663,347 to 13,726,663, reverse strand). Ensembl gene ENSG00000177150.
Subcellular location: Mitochondrion inner membrane; Cytoplasm
Subcellular location (Human Protein Atlas): Golgi apparatus; Mitochondria; Nucleoplasm
Gene Ontology:
Molecular function: metalloendopeptidase inhibitor activity
Biological process: adaptive thermogenesis; mitochondrial inner membrane fusion
Cellular component: mitochondrion; cytoplasm; mitochondrial inner membrane
Genetic constraint (gnomAD): Loss-of-function variants: 11 observed, 23.96 expected, observed/expected ratio (o/e) 0.46, 90% interval 0.29 to 0.76. The upper end of that interval is the gene's LOEUF score, 0.76, which puts it in group 3 of 6, group 1 being the genes least tolerant of losing a copy. Missense variants: 309 observed, 331.19 expected, observed/expected ratio (o/e) 0.93, 90% interval 0.85 to 1.02. Synonymous variants: 123 observed, 122.16 expected, observed/expected ratio (o/e) 1.01, 90% interval 0.87 to 1.17.
Homologues: Orthologues: chimpanzee FAM210A (100% identical), macaque FAM210A (97% identical), dog FAM210A (87% identical), rabbit FAM210A (85% identical), pig FAM210A (85% identical), guinea pig FAM210A (81% identical), mouse Fam210a (78% identical), rat Fam210a (78% identical), tropical clawed frog fam210a (54% identical), zebrafish fam210aa (50% identical), zebrafish fam210ab (46% identical), Drosophila melanogaster CG14613 (27% identical), and 1 more. Paralogues in human: MIMS2 (17% identical).
Diseases named in the same sentence as MIMS1 in open-access papers:
MIMS1 is named in the same sentence as 8 diseases in open-access papers, as found by Europe PMC text mining. Sharing a sentence is not in itself a finding about the gene and the disease.
MIMS1 shares sentences with these, for which no sentence is quoted: heart disease (2 papers); heart failure (2); tumor (2); cancer (1); cardiac hypertrophy (1); melanoma (1); myocardial infarction (1); sarcopenia (1).